FMO2 (flavin containing dimethylaniline monoxygenase 2)
Description:
Catalyzes the oxidative metabolism of numerous xenobiotics, including mainly therapeutic drugs and insecticides that contain a soft nucleophile, most commonly nitrogen and sulfur and participates to their bioactivation. Specifically catalyzes S-oxygenation of sulfur derived compounds such as thioureas-derived compounds, thioetherorganophosphates to their sulfenic acid. In vitro, catalyzes S-oxygenation of the second-line antitubercular drugs thiacetazone (TAZ) and ethionamide (ETA), forming a sulfinic acid and a carbodiimide via a postulated sulfenic acid intermediate. Also catalyzes S-oxygenation of the thioether-containing organophosphate insecticides, phorate and disulfoton.
Synonyms: FMO1B1
Tractability: Antibody: UniProt predicts a signal peptide or a membrane-spanning region. PROTAC: UniProt records ubiquitination sites on it.
Gene: Protein-coding gene on chromosome 1 (171,185,249 to 171,212,686, forward strand). Ensembl gene ENSG00000094963.
Subcellular location: Microsome membrane; Endoplasmic reticulum membrane
Pathways (Reactome):
Metabolism: FMO oxidises nucleophiles
Gene Ontology:
Molecular function: N,N-dimethylaniline monooxygenase activity; flavin adenine dinucleotide binding; monooxygenase activity; NADP binding
Biological process: NADP+ metabolic process; sulfur oxidation; toxin metabolic process; xenobiotic metabolic process
Cellular component: membrane; endoplasmic reticulum membrane
Genetic constraint (gnomAD): Loss-of-function variants: 21 observed, 30.95 expected, observed/expected ratio (o/e) 0.68, 90% interval 0.48 to 0.98. The upper end of that interval is the gene's LOEUF score, 0.98, which puts it in group 4 of 6, group 1 being the genes least tolerant of losing a copy. Missense variants: 470 observed, 497.83 expected, observed/expected ratio (o/e) 0.94, 90% interval 0.88 to 1.02. Synonymous variants: 162 observed, 175.95 expected, observed/expected ratio (o/e) 0.92, 90% interval 0.81 to 1.05.
Homologues: Orthologues: chimpanzee FMO2 (99% identical), macaque FMO2 (97% identical), pig FMO2 (88% identical), rabbit FMO2 (87% identical), dog FMO2 (86% identical), mouse Fmo2 (86% identical), rat Fmo2 (85% identical), guinea pig FMO2 (82% identical), tropical clawed frog fmo1 (54% identical), Caenorhabditis elegans fmo-1 (41% identical), Caenorhabditis elegans fmo-5 (40% identical), Caenorhabditis elegans fmo-3 (40% identical), and 2 more. Paralogues in human: FMO1 (57% identical), FMO3 (56% identical), FMO5 (56% identical), FMO4 (54% identical), FOXRED2 (20% identical).
Diseases named in the same sentence as FMO2 in open-access papers:
FMO2 is named in the same sentence as 26 diseases in open-access papers, as found by Europe PMC text mining. Sharing a sentence is not in itself a finding about the gene and the disease. The quoted sentences say what the papers report.
lung adenocarcinoma (4 papers, 2017 to 2022). A carcinoma that arises from the lung and is characterized by the presence of malignant glandular epithelial cells. "FMO2 is a NADPH-dependent enzyme implicated in oxidation reactions and plays a possible role in lung adenocarcinoma." (PMID 35565312, 2022). "Although the role of FMO2, whose main function is an NADPH-dependent enzyme, in tumorigenesis is still unclear, it has been reported to play a role as a tumor suppressor in lung adenocarcinoma." (PMID 35354498, 2022). "The expressions of PDK4, FMO2, and FABP4 are significantly downregulated in lung adenocarcinoma compared to normal lung tissue in several datasets, and this phenomenon was also observed in GSE10072 array." (PMID 29285217, 2017). "The analysis of the effects from each gene expression on survival outcome indicated that 6 genes (AGR2, SPDEF, CDKN2A, CLDN3, SFN, and PHLDA2) play oncogenic roles, and 7 genes (PDK4, FMO2, CPED1, GNG11, IL33, BTNL9, and FABP4) act as tumor suppressors in lung adenocarcinoma." (PMID 29285217, 2017). "However, since the genetic interactions of hsa-miR-183-5p-BTNL9, hsa-miR-33b-5p-CPED1, hsa-miR-429-CPED1, hsa-miR-182-5p-FMO2, hsa-miR-130b-5p-IL33, and hsa-miR-542-3p-IL33 have not been identified, these altered genetic regulations may play important roles in the progression of lung adenocarcinoma." (PMID 29285217, 2017).
breast carcinoma (2 papers, 2023 to 2025). "A new high-throughput drug metabolizing enzymes and transporters microarray platform revealed that single nucleotide polymorphism in FMO2 was significantly associated with docetaxel-induced febrile neutropenia in Lebanese breast cancer patients." (PMID 37963835, 2023). "In SCAN-B, FMO2 was upregulated in ER-, PR-, and ER-/PR- breast cancer (P < 0.0001, = 0.0006, and < 0.0001, respectively), which was consistent with TCGA." (PMID 37963835, 2023). "In the TCGA database, FMO2 was downregulated in breast cancer compared to healthy and tumor-adjacent (P < 0.0001)." (PMID 37963835, 2023). "In addition, we excavated secreted Frizzled-related protein 1 (SFRP1), a known negative regulator of the Wnt/β-catenin pathway, from the perspective of co-expression analysis to reveal the potential molecular mechanism of FMO2 in breast cancer." (PMID 37963835, 2023). "Therefore, in the present study, we evaluated the FMO2 expression and its prognostic potential and immunotherapeutic response in breast cancer by comprehensive bioinformatics analysis." (PMID 37963835, 2023). "Similarly, FMO2 was upregulated in ER-/PR- breast cancer (P = 0.0002)." (PMID 37963835, 2023). "Finally, we validated the co-expression profile of FMO2 and SFRP1 in 8246 patients with breast cancer with DNA microarrays data and 4421 patients with breast cancer with RNA-sequence data from bc-GenExMiner and 1284 patients with breast cancer with TCGA breast cancer data from UCSC Xena." (PMID 37963835, 2023).
tuberculosis (2 papers, 2017 to 2024). A chronic, recurrent infection caused by the bacterium Mycobacterium tuberculosis. "the FMO2 gene as an immune regulatory factor, may play a role in their resistance to tuberculosis." (PMID 39233740, 2024). "The human FMO2 (flavin-containing monooxygenase 2) gene has been shown to be involved in innate immunity against microbial infections, including tuberculosis (TB), via the modulation of oxidative stress levels." (PMID 28981537, 2017).
cognitive decline (1 paper, 2025). "Our investigations reveal that aging differentially modulates restraint stress-induced ER stress responses: while suppressing the upregulation of protective ER stress-related genes (Fmo2, Creb3l1, Tmtc3, Bak1), it promotes the induction of Pgap1 change associated with cognitive decline." (PMID 41200271, 2025).
heart failure (1 paper, 2022). Inability of the heart to pump blood at an adequate rate to meet tissue metabolic requirements. "Studies performed in male mice with genetic inhibition of Fmo2 showed that this enzyme has a critical role in converting choline to TMAO during heart failure, and revealed that TMAO suppresses cardiac metabolism by inhibiting mitochondrial complex IV." (PMID 36050466, 2022).
ischemic disease (1 paper, 2025). Lack of blood supply to an area of the body, resulting in impairment of tissue oxygenation. "To verify the alteration of Fmo2 in other ischemic diseases, we used a publicly available database containing scRNA‐seq data of hindlimb ischemia (HLI) models." (PMID 41053533, 2025).
ischemic heart diseases (1 paper, 2024). "Taken together, this study provides mechanistic insights into the role of FMO2 in oxidative protein folding and highlights the critical function of this enzyme in ischemic heart diseases." (PMID 39480513, 2024).
transaldolase deficiency (1 paper, 2017). Transaldolase deficiency is an inborn error of the pentose phosphate pathway that presents in the neonatal or antenatal period with hydrops fetalis, hepatosplenomegaly, hepatic dysfunction, thrombocytopenia, anemia, and renal and cardiac abnormalities. "To determine if FMO-2 activation contributes to the lifespan extension from transaldolase deficiency, we treated fmo-2(ok2147) mutants with tald-1(RNAi)." (PMID 28355222, 2017).
trimethylaminuria (1 paper, 2024). A rare inborn error of metabolism characterized by the presence of large amounts of trimethylamine in urine, sweat, and breath, resulting in a fishy body odor in affected individuals. "The duplicated regions harbor a total of five protein-coding genes: MROH9 and members of the flavin-containing monooxygenase family, including FMO3 (mutations cause the recessive disorder Trimethylaminuria; MIM 602079), FMO2, FMO1, and FMO4, all located within the chr1_D region." (PMID 39257002, 2024).
infection (9 papers, 2012 to 2025). The state of being infected such as from the introduction of a foreign agent such as serum, vaccine, antigenic substance or organism. "Remarkably, mutations of either cofactor binding motif caused infection survival defects that were barely weaker than that of null fmo-2/FMO5 mutants." (PMID 33978570, 2021). "Our prior studies also showed that infection causes fmo-2/FMO5 induction independently of previously identified host defense pathways, including p38 MAPK, TGF-β, ERK, insulin, Wnt, and HIF-1 pathways." (PMID 33978570, 2021). "To determine the physiological relevance of fmo-2/FMO5 during infection, we examined mutants homozygous for an fmo-2/FMO5 deletion predicted to result in a null allele (C. elegans Deletion Mutant Consortium, 2012)." (PMID 33978570, 2021). "Interestingly, upon infection with common human pathogenic bacteria such as P. aeruginosa, S. aureus, and Enterococcus faecalis, many upregulated genes including icl-1, fmo-2, and acs-2, are regulated by NHR-49, revealing a role for this transcription factor in the innate immune response." (PMID 37645565, 2023). "fmo-2 is induced by and required for survival after infection with S. aureus and E. faecalis, but is downregulated after infection with P. aeruginosa." (PMID 37645565, 2023). "C. elegans fmo-2 is induced by oxidative stress, starvation, and pathogen infection in an nhr-49-dependent fashion." (PMID 35285794, 2022). "This discovery is related to prior studies that showed that Enterococcus faecalis, an enteric Gram-positive human pathogen unrelated to S. aureus, induces fmo-2/FMO5 during infection of C. elegans." (PMID 33978570, 2021). "Deletion of fmo-2/FMO5 severely compromised infection survival, thus identifying the first FMO with innate immunity functions in animals." (PMID 33978570, 2021). "Simultaneous deletion of nhr-49/PPARA and fmo-2/FMO5 resulted in similarly impaired infection survival as the single mutants, suggesting that nhr-49/PPARA and fmo-2/FMO5 function in the same pathway." (PMID 33978570, 2021). "Because hlh-30/TFEB and nhr-49/PPARA contributed to both infection-specific fmo-2/FMO5 induction and each other’s expression, we examined their genetic interactions." (PMID 33978570, 2021). "Our study reveals another role of NHR-49 during infection wherein it regulates the production of many immune effectors, of which, FMO-2 directly regulates survival." (PMID 32482643, 2020). "nhr-49 is required to induce fmo-2 in various stresses and infection models." (PMID 35285794, 2022). "In addition, we found that intestinal-restricted fmo-2/FMO5 overexpression was sufficient to boost infection survival." (PMID 33978570, 2021). "But, we found fmo‐2 to be downregulated by PA14 infection, whereas acs‐2 showed a small increase." (PMID 34156142, 2021). "Thus, it is possible that FMO-2/FMO5 is an infection-specific NADPH oxidase that generates H2O2 with antimicrobial and signaling functions." (PMID 33978570, 2021). "Together, these data indicated that FMO-2/FMO5 catalytic activity may be specifically required for host defense against infection." (PMID 33978570, 2021). "To test whether FMO-2 serves an immune effector function, we tested the survival of fmo-2 RNAi animals upon infection with OG1RF." (PMID 32482643, 2020). "In addition, other genes highly induced by rnp-6 RNAi, such as lys-3 and fmo-2, were unaffected by the rnp-6 G281D substitution under infection conditions." (PMID 32538777, 2020). "In addition, we found that loss of FMO-2/FMO5 causes a severe defect in infection survival without affecting longevity." (PMID 33978570, 2021). "In more recent studies, oxidative stress and infection with either Pseudomonas aeruginosa (PA14) or Staphylococcus aureus was found to induce fmo-2, with FMO-2 required for pathogen resistance." (PMID 41241700, 2025). "Upon infection, both gain-of-function mutants exhibited further fmo-2/FMO5 induction, reaching higher fmo-2/FMO5 expression than wild type controls." (PMID 33978570, 2021).
infection (continued). "As the most highly induced infection-specific gene in hlh-30/TFEB mutants, fmo-2/FMO5 attracted our attention." (PMID 33978570, 2021). "During infection, NHR-49/PPAR-α appeared to be essential for fmo-2/FMO5 expression in the whole animal, while hlh-30/TFEB was partially dispensable in the intestine and pharynx." (PMID 33978570, 2021). "Consistent with the survival results, rnp-6 RNAi strongly induced the expression of numerous infection responsive genes, including nlp-34, lys-3, irg-2, irg-1, M01G12.9, fmo-2 and cyp-37B1." (PMID 32538777, 2020). "Recent work also supported a role for fmo-2 in C. elegans innate immunity, as it’s transcription was strongly induced via NHR-49 and HLH-30 in a pathogen-specific manner to impact infection survival." (PMID 41241700, 2025). "In contrast, introduction of fmo-2(-) in the two nhr-49(gof) mutant backgrounds almost completely suppressed the enhanced infection survival, while their lifespan on nonpathogenic E. coli was also suppressed (for gf1) or slightly impaired (for gf2)." (PMID 33978570, 2021). "While these genes are critical for survival upon E. faecalis (acs‐2 and fmo‐2) or S. aureus (fmo‐2) infection, neither one contributed toward PA14 resistance or glp‐1 longevity." (PMID 34156142, 2021). "Deletion of fmo-2/FMO5 did not affect the induction of the nine most highly induced infection-specific signature genes." (PMID 33978570, 2021). "Therefore, elucidation of mechanisms of host defense mediated by FMO-2 in nematodes and FMO5 in mammals will provide fundamental insight into evolutionarily conserved mechanisms of host defense against infection and identify therapeutic opportunities for infections and inflammatory diseases." (PMID 33978570, 2021). "After infection, nhr-49/PPARA mutants completely failed to induce fmo-2/FMO5." (PMID 33978570, 2021).
tumor (7 papers, 2006 to 2023). "We found that FMO1 and FMO2 expression was associated with three and nine types of tumor-infiltrating immune cells, respectively." (PMID 37274237, 2023). "Five genes, ROBO4, SNRK, TM4SF1, FMO2 and TIMP3, found in this screen have been preferentially associated with capillary endothelial cells from mouse lung and TMBM expression was found specifically in tumour endothelial cells, but not normal endothelial cells." (PMID 16390543, 2006).
cancer (3 papers, 2017 to 2023). A tumor composed of atypical neoplastic, often pleomorphic cells that invade other tissues. "The pan-cancer analysis in TCGA and GEO datasets showed that FMO1 was upregulated, while FMO2 and FMO4 were downregulated in GC." (PMID 37274237, 2023).
FMO2 also shares sentences with these, for which no sentence is quoted: lung carcinoma (2 papers); bacterial infection (1); cardiovascular disease (1); cholestasis (1); cutaneous squamous cell carcinoma (1); energy metabolism disorder (1); Hypertension (1); immune deficiency (1); invasive ductal breast carcinoma (1); ischemia (1); meningioma (1); myocardial infarction (1); oropharyngeal squamous cell carcinoma (1); ovarian carcinoma (1).